CRP (C-reactive protein)
Diseases named in the same sentence as CRP in open-access papers (continued):
Sharing a sentence is not in itself a finding about the gene and the disease.
endothelial dysfunction (continued). "Stronger evidence supports the role of periodontal inflammation and oral microbiota dysbiosis in systemic inflammatory burden, with elevated mediators such as CRP, IL-6, TNF-α, and IL-1β implicated in endothelial dysfunction and atherogenesis." (PMID 41294894, 2025). "Mid Phase (2010-2020): Research focus shifted towards cellular phenotypic functions and inflammatory biomarkers, with keywords such as “C-reactive protein”, “endothelial dysfunction”, and “mitochondrial dysfunction” emerging as key topics." (PMID 40513070, 2025). "Several biomarkers, including integrins, selectins, cadherins, homocysteine, interleukin (IL)-8, IL-18, and C-reactive protein (CRP), have been proposed to reflect endothelial dysfunction." (PMID 41464233, 2025). "Repetitive intermittent hypoxemia and hypercapnia promote oxidative stress, endothelial dysfunction, and systemic inflammation, accelerating atherogenesis and plaque instability (elevated CRP, ADMA)." (PMID 41303825, 2025). "In detail, the key pro-inflammatory cytokine, IL-6, triggers the liver to produce CRP, which, in turn, promotes leukocyte recruitment and inflammatory signaling in endothelial cells, leading to endothelial dysfunction (ED)." (PMID 40722588, 2025). "C-reactive protein (CRP) and endothelial dysfunction with elevated gut permeability are also linked to TMAO." (PMID 40491716, 2025). "Biochemical values like D-dimer, CRP, and ferritin serve as important indicators of enhanced systemic inflammation and endothelial dysfunction." (PMID 40142738, 2025). "CRP is an acute-phase protein that reflects systemic inflammation and directly contributes to endothelial dysfunction by inhibiting nitric oxide production, increasing oxidative stress, and promoting vascular stiffness." (PMID 40408377, 2025). "Recent evidence supports that periodontal inflammation contributes to systemic endothelial dysfunction and plaque instability through inflammatory mediators such as C-reactive protein (CRP), interleukin-6 (IL-6), and tumor necrosis factor-α (TNF-α)." (PMID 41303261, 2025). "Migraine is increasingly recognized as a neurovascular disorder characterized by episodic endothelial dysfunction, transient inflammatory activation (including interleukin-6 and CRP surges), oxidative stress, and—in many patients—hormonal fluctuations." (PMID 41440551, 2025). "CRP, produced in the liver under IL-6 stimulation, actively contributes to endothelial dysfunction by enhancing leukocyte adhesion." (PMID 41007869, 2025). "It is suggested that periodontitis is positively linked with a systemic host response and with a low-grade inflammatory state, as assessed by raised serum levels of CRP and endothelial dysfunction." (PMID 38196480, 2024). "By stimulating the synthesis of acute phase reactants especially CRP, coagulation cascade, endothelial dysfunction, perpetuation of inflammatory responses and effects on lipid metabolism, IL‐6 can lead to the development and acceleration of CVD occurrence." (PMID 39160453, 2024). "Earlier studies have focused on endothelial dysfunction-related biomarkers, such as CRP, IL-6, and NLR, which reflect systemic inflammation and are widely reported in various non-central nervous system diseases." (PMID 38539657, 2024). "Our findings demonstrate that CRP alone cannot fully induce the expression of endothelial dysfunction biomarkers, suggesting other risk factors of cardiovascular disorders are necessary to be involved to induce endothelial dysfunction with CRP." (PMID 38627621, 2024). "Endothelial dysfunction in dogs has been assessed by levels of C-reactive protein (CRP), nitrate and nitrite (NOx), l-arginine (l-Arg), asymmetric dimethylarginine (ADMA), symmetric dimethylarginine (SDMA), and the von Willebrand factor (vWF)." (PMID 39451250, 2024).
endothelial dysfunction (continued). "Biomarkers such as C-reactive protein (CRP) and endothelial dysfunction markers have been identified as shared indicators of cardiovascular risk in radiation-exposed populations and aging individuals." (PMID 38392316, 2024). "Scientific evidence also suggests that inflammation (interleukin-6 and C-reactive protein), oxidative stress, and endothelial dysfunction play important roles in the pathogenesis of frailty." (PMID 39733527, 2024). "Concurrently, a decrease in inflammation markers, notably C-reactive protein (CRP) and interleukin-6 (IL-6), implies the attenuation of chronic inflammation, potentially reducing endothelial dysfunction, thrombotic events, and organ fibrosis." (PMID 38327940, 2024). "The interplay between endothelial dysfunction, oxidative stress, and inflammatory mediators, including C-reactive protein and cytokines, suggests a systemic process that extends beyond localized vascular damage." (PMID 39769057, 2024). "Long night periodical hypoxia episodes determine inflammation with oxidative stress and release of systemic inflammatory mediators like TNF-α, IL-6, IL-8, and CRP, which lead to endothelial dysfunction and atherosclerotic plaque formation." (PMID 39585008, 2024). "It was demonstrated that CRP reduced the expression of eNOS (both gene and protein) in vitro in human aortic endothelial cells (HAECs), suggesting the direct participation of CRP in the development of endothelial dysfunction." (PMID 38627621, 2024). "Dissatisfaction with the workplace induces elevated levels of the endothelial dysfunction markers hs-CRP and AUER." (PMID 39064476, 2024). "CRP can induce endothelial dysfunction by inhibiting the AMP-activated protein kinase endothelial nitric oxide synthase (AMPK-eNOS) signaling pathway." (PMID 39596339, 2024). "Decreased lung function or resultant pulmonary hypertension correlates with endothelial dysfunction and increased levels of inflammatory mediators, such as C-reactive protein, interleukin-6, interleukin-8, and tumor necrosis factor-alpha." (PMID 38911586, 2024). "Nonetheless, our findings confirm those of previous studies reporting that PTX‐3 is a more sensitive marker of endothelial dysfunction compared to CRP." (PMID 39414396, 2024). "CRP induces endothelial dysfunction by directly destroying the blood–brain barrier (BBB) and induces monocytes to release proinflammatory cytokines, leading to increased vascular permeability and cerebral hemorrhage." (PMID 37077571, 2023). "CRP, a marker of endothelial dysfunction during inflammation due to infection and chronic cardiovascular disorders, is an essential indicator of the severity of COVID-19 infection, as demonstrated by multiple studies." (PMID 38127882, 2023). "Statins improve endothelial dysfunction and decrease C-reactive protein (CRP), which reflects inflammatory processes, oxidative stress and oxidized LDL levels in atheroma, all of which are involved in HF and complicate its pathogenesis." (PMID 37512127, 2023). "A case–control study also investigated the endothelial dysfunction by the persistent pro-inflammatory state from periodontitis, finding higher CRP rates in patients with severe periodontitis." (PMID 37568542, 2023). "There was also no change in insulin sensitivity, low-grade inflammation and endothelial dysfunction, in addition to an increase in C-reactive protein (CRP) after 3 months of probiotic consumption." (PMID 37296485, 2023). "Endothelial dysfunction and hyperinflammation increased vascular permeability and decreased sodium, albumin, and phosphate levels, while elevating CRP, fibrinogen, D-dimers, and proBNP." (PMID 37646033, 2023). "Flow-mediated dilation (FMD) and reactive hyperemia index (RHI) were used to assess endothelial dysfunction, and we assayed high-sensitivity C-reactive protein, interleukin-6, fibrinogen, p-selectin, and myeloperoxidase as serum measures of inflammation." (PMID 37305426, 2023).
endothelial dysfunction (continued). "SVCAM-1 is correlated with high-sensitivity C-reactive protein (hs-CRP) levels, which means that inflammation is associated with endothelial dysfunction." (PMID 37298632, 2023). "It is also possible that elevated CRP levels lead to fibrinolytic resistance and endothelial dysfunction by affecting fibrin clot structure, highlighting its prothrombogenic effects on injured vessel walls." (PMID 37873776, 2023). "Low-grade chronic inflammation with high levels of C reactive protein (CRP), endothelial dysfunction, and high oxidative stress contribute further to the complexity of pathogenesis of polycystic ovary syndrome." (PMID 36900051, 2023). "Endothelial dysfunction can be promoted by leptin, FT4, insulin and CRP while adiponectin improves endothelial dysfunction by inducing the production of nitric oxide." (PMID 36520252, 2023). "As biomarkers with hypercoagulation, we measured PAI-1, a marker of endothelial dysfunction, and P-selectin, a marker of platelet activation, in addition to the routine biological parameters (CRP, D-dimer, and ferritin)." (PMID 37908357, 2023). "In patients with CKD, an increase in lipid peroxidation due to elevated levels of the nitric oxide synthase inhibitor, asymmetric dimethylarginine, leads to elevated CRP, oxidative stress, and endothelial dysfunction." (PMID 37784041, 2023). "MR-proADM also showed a strong correlation with systemic inflammation markers such as CRP, IL6, and TNFα, as well as significant associations with endothelial dysfunction biomarkers (SDMA, ADMA, and C-CTproET1)." (PMID 37626802, 2023). "Single intravenous injectionof CRP in a mouse model contributed to endothelial dysfunction and hypertensionby inhibiting NO release." (PMID 39077585, 2023). "Endothelial dysfunction, systemic inflammation and immune response, including C-reactive protein, interleukins, thrombotic markers and antibodies, have all been observedin patients with PD and CVD." (PMID 37745126, 2023). "In order to assess the contribution of inflammation as well as endothelial dysfunction, we first measured the serum levels of C-reactive protein (CRP) and Vascular Cell Adhesion Molecule-1 (sVCAM-1), respectively." (PMID 37398656, 2023). "Patients with low testosterone were also more likely to exhibit atherosclerotic plaques, endothelial dysfunction, and higher levels of C reactive protein (CRP) indicating an inflammatory response." (PMID 36596999, 2023). "In order to characterize the inflammatory state and the endothelial dysfunction in our cohort of patients, we measured soluble Vascular Cell Adhesion Molecule-1 (sVCAM-1) and C-reactive protein (CRP) in their serum samples." (PMID 37398656, 2023). "PCOS per se has been viewed as a state of chronic low-grade inflammation with increased production of specific cytokines and chemokines such as TNFα, IL-1, IL-6, follistatin, CRP, and adhesion molecules involved in endothelial dysfunction." (PMID 35564864, 2022). "Nevertheless, in male and female patients, symptomatic peripheral diabetic neuropathy and inflammation are related to endothelial dysfunction and elevated CRP serum levels." (PMID 35620114, 2022). "This prothrombotic state is possibly related to the increase in inflammatory cytokine levels (high sensitivity C-reactive protein (CRP), IL-6 and TNF-α), which are proatherogenic, decrease endothelial progenitor cell survival and cause endothelial dysfunction." (PMID 35207718, 2022). "Eventually, serum tumor necrosis factor-α (TNF-α), interleukin-6 (IL-6), and C-reactive protein (CRP), which respond to inflammatory levels, were eventually elevated, indicating a link between the inflammatory response caused by IR and endothelial dysfunction." (PMID 36589857, 2022). "In patients treated with antidiabetic medications with bona fide anti-inflammatory properties, reduced CRP, inflammatory cytokines, and endothelial dysfunction, along with increased adiponectin were observed." (PMID 36013507, 2022).
endothelial dysfunction (continued). "CRP stimulates the production of cellular adhesion molecules, enhances cellular apoptosis and leads to endothelial dysfunction and then, arterial stiffness." (PMID 35748644, 2022). "The results of previous studies demonstrated a positive relationship between circulating ADMA levels and IL-6 and CRP levels, indicating that inflammation and endothelial dysfunction are two parallel processes." (PMID 35330470, 2022). "Meanwhile, the T allele of rs7396366, whose closest gene is AP2A2, had an association with increased plasma C-reactive protein (CRP), which is a biomarker in acute CHD and endothelial dysfunction." (PMID 35055468, 2022). "More importantly, our data show that global inflammation (CRP) and a hypercoagulable state (D-dimer) were present in concomitance with endothelial dysfunction and that these alterations still persisted at 2–4 months from the onset of the acute infection." (PMID 34207876, 2021). "In the experimental models, the influence of CRP on the onset of endothelial dysfunction, increasing expression of adhesion molecules, and on the recruitment of monocytes into the vessel wall was demonstrated." (PMID 33407375, 2021). "The mechanisms leading to endothelial dysfunction in IBD include chronically increased levels of pro-inflammatory cytokines (CRP, IL-6, TNF-α and oxidative stress." (PMID 34444821, 2021). "Increased RAS activity (renin), endothelial dysfunction (vWF), coagulation parameters (D-dimer, prothrombin fragment F1,2) and inflammation (CRP, IL-6) were significantly altered in COVID patients and followed similar trends from mild-COVID to ARDS-COVID." (PMID 34945736, 2021). "Malondialdehyde (MDA) is an end product of lipoperoxidation, which increases the level of pro-inflammatory cytokines such as interleukins and C-reactive protein (CRP) to establish a pro-atherogenic environment that results in endothelial dysfunction." (PMID 34368206, 2021). "Previous observational studies have shown positive associations of TyG index with inflammatory indicators of white blood cells and C-reactive protein, and high TyG index is related to endothelial dysfunction, inflammation response, and oxidative stress." (PMID 34030657, 2021). "At the same time, the elevated level of inflammatory cytokines and serum C-reactive protein (CRP) in periodontitis patients plays a role in endothelial dysfunction." (PMID 35128525, 2021). "Inflammation and its associated inflammatory cytokines, including IL-6, TNF-α, IL-1β, and inflammatory factors like C-reactive protein (CRP), are all known to induce endothelial dysfunction in AT." (PMID 32806722, 2020). "Increased CRP levels result in endothelial dysfunction, which induces vasoconstrictive, prothrombotic, and proinflammatory pathways." (PMID 33193910, 2020). "The cardiovascular effects of CRP have been described mainly through endothelial dysfunction by reducing nitric oxide levels." (PMID 31939522, 2020). "Our study found lower VEGF-A and higher CRP serum concentrations in patients with excess body mass, accompanied by markers of endothelial dysfunction, such as higher SI and lower PPT." (PMID 32046348, 2020). "Inflammation-induced endothelial dysfunction is thought to be mediated by elevated C-reactive protein (CRP) levels." (PMID 32899944, 2020). "Accordingly, CRP promotes endothelial dysfunction by inhibiting nitric oxide production to impair endothelial-dependent vascular relaxation." (PMID 32358950, 2020). "Markers of inflammation (IL-6, TNF-α, CRP), innate defense (cathelicidin), monocyte and macrophage activation (sCD14, sCD163 and, IL-2sRα), endothelial dysfunction (ET-1) and general immune health (CD4/CD8 ratio) were associated with lung abnormalities in HIV." (PMID 31830103, 2019). "Obese children, in general, have higher concentrations of leptin and CRP and are vulnerable for endothelial dysfunction." (PMID 31466225, 2019).
endothelial dysfunction (continued). "The progression of WMHs in CSVD has been associated with higher expressions of ICAM1, CRP, and MMP9, thus supporting the role of endothelial dysfunction in CSVD." (PMID 31708793, 2019). "During the inflammatory process, the organism produces molecules, such as C-reactive protein (CRP) and free radicals, which are able to decrease the production or bioavailability of NO leading to endothelial dysfunction." (PMID 31337127, 2019). "CRP directly induces endothelial dysfunction through a reduction in nitric oxide production and favors oxidative stress." (PMID 31133882, 2019). "Inflammatory biomarkers of endothelial dysfunction, such as C-reactive protein (CRP), interleukin-6 (IL-6), intracellular adhesion molecule-1 (ICAM1), and E-selectin, have been widely studied and associated with CSVD in human and animal models." (PMID 31708793, 2019). "We only measured CRP, sICAM-1, sVCAM-1 and sE-selectin, which reflect just a part of the complex and multifaceted process of arterial remodelling induced by endothelial dysfunction and inflammation." (PMID 29101422, 2018). "There was also a strong relation between inflammation (CRP), endothelial dysfunction markers (ADMA), and the effect of these factors on the progression of vascular changes in patients with baseline normal IMT." (PMID 29682152, 2018). "A positive correlation among CRP concentrations, endothelial dysfunction, and the severity of the atherosclerotic process have been reported in several studies." (PMID 30595838, 2018). "Other potential serum biomarkers related to the endothelial dysfunction and inflammation are the nitric oxide, the soluble vascular cell adhesion molecule-1, the high-sensitivity C-reactive protein, the tumour necrosis factor-α, the IL-6 and the P-selectin." (PMID 28933368, 2017). "D-dimers correlated independently with C-reactive protein and studied markers of endothelial dysfunction." (PMID 28368336, 2017). "These abnormalities correlated with both inflammation (as reflected by C-reactive protein concentrations) and endothelial dysfunction (as reflected by the concentrations of angiopoietin-2 and sFlt-1)." (PMID 28368336, 2017). "It has been proposed that CRP can impact on vascular stiffness by means of its role in endothelial dysfunction and thereby lead to disruption of structural regulation of arteries and consequently arterial stiffness." (PMID 28759613, 2017). "The molecular targets through which aging perturbs vascular homeostasis are manifold and appear to include increased expression or activation of TNF-α, IL-1β, IL-6 family members and CRP, which promote inflammation and endothelial dysfunction." (PMID 28840062, 2017). "Jee & Jin (2012) also demonstrated increased endothelial dysfunction markers, mainly sE-selectin, which was associated with leukocyte trafficking, exercise intensity, TNF-α, CRP, and CK." (PMID 27911915, 2016). "Microalbuminuria as a marker of early renal damage reflects widespread vascular damage (microangiopathy), a pro inflammatory state (with increased levels of IL-6, TNF-α, CRP and fibrinogen) and ensuing endothelial dysfunction." (PMID 25971452, 2015). "The FBG, HbA1C, Hcy and hs-CRP in patients with endothelial dysfunction were significantly higher than those in patients with normal endothelial function (P<0.05 for all)." (PMID 26150839, 2015). "Sociodemographic, inflammatory markers (IL-6, TNF-?, CRP-us), endothelial dysfunction (flow-mediated vasodilatation - FMD), body composition (DXA) and the 25-hidroxi-vitamin D parameters were analyzed." (PMID 26395776, 2015). "C-reactive protein (CRP), a very sensitive marker of inflammation produced by the liver cells in response to various stimuli, is involved in endothelial dysfunction and angiogenesis which have been proposed to play an important role in the pathogenesis of DR." (PMID 25887518, 2015).